CR1 (complement C3b/C4b receptor 1 (Knops blood group))
Diseases named in the same sentence as CR1 in open-access papers (continued):
Sharing a sentence is not in itself a finding about the gene and the disease.
cancer (32 papers, 2011 to 2025). A tumor composed of atypical neoplastic, often pleomorphic cells that invade other tissues. "The results showed the positive CR‐1 expression was associated with low differentiation and advanced stage of cancer (p = 0.028, 0.024, respectively)." (PMID 37528674, 2023). "Studies have shown that CR1 protein was implicated in the invasion and metastasis potential of many human cancers." (PMID 37528674, 2023). "In conclusion, our results suggest that CR‐1 overexpression is significantly associated with cancer recurrence." (PMID 37528674, 2023). "As for other cancer vaccines, the basic idea underlying CR-1 vaccination is to induce the production of Abs that are able to block CR-1 and Nodal signaling in cancer (stem) cells." (PMID 34360603, 2021). "Numerous studies have found CR-1 and/or Nodal constitutively overexpressed in various human cancers, where their high expression is strongly associated with a worse prognosis." (PMID 34360603, 2021). "Reactivation of CR-1 in adult tissues has been associated with various cancer types." (PMID 31455359, 2019). "Considering the important role of CR1 in complement activation, innate immunity and chronic inflammation, CR1 has emerged as a molecule of immense interest in gaining insight into the susceptibility to cancer." (PMID 24621201, 2014). "This is mainly explained by overexpression of CRIPTO in these cells (also referred to as CR-1 or TDGF1), an embryonic factor associated with metastatic potential, cancer stem cell maintenance, and EMP." (PMID 40427042, 2025). "Further, SFN inhibits cell proliferation and mammosphere formation of CSCs in TNBC by decreasing the expression of cancer-specific CR1 and CRIPTO-3/TDGF1P3 genes." (PMID 40013196, 2025). "We found that C3AR1 expression is higher in GBM as compared with all other cancers analyzed in TCGA, whereas Complement Receptor 1 (CR1), CR2, C1qR1 (CD93), and C5AR1 were expressed at varying levels." (PMID 39172519, 2024). "Despite dysregulation in certain cancers, the expression levels of CR1 and PMFBP1 remained at a superficial level." (PMID 39434140, 2024). "CR1 was shown to be highly expressed in human cancers of the lung, colon, breast, skin, stomach, pancreas, bladder, gall bladder, ovary, cervix, endometrium, prostate, and testis." (PMID 39518018, 2024). "This study supports the results of more and more literatures that the expression of CR‐1 is related to the prognosis of cancer." (PMID 35949510, 2022). "Five genes, AXIN2, BMP1, CR1, ERBB2, and RYR1, have been recorded of association with birth defects and cancer." (PMID 36384586, 2022). "The expression level of CR-1 is enhanced in various tumors supporting cancer cell proliferation, migration, epithelial–mesenchymal transition and stimulation of tumor angiogenesis, while it is very low in normal adult tissues." (PMID 33567764, 2021). "Spheroid-cultured Tubo cells isolated by BALB-neuT primary tumors develop a cancer stem cell signature characterized by high CR-1 expression levels." (PMID 34360603, 2021). "CR-1 is a multifunctional gene that plays an essential role in embryogenesis as well as cancer growth and progression." (PMID 34517344, 2021). "The isolated phage clones with the affinity to CR-1 protein were assessed for the potential of targeting cancer cells and suppressing the cell growth." (PMID 33567764, 2021). "The aim of this review is to clarify the role of CR-1 and Nodal in cancer stem populations and to summarize the current therapeutic strategy to target CSCs using monoclonal antibodies (mAbs) or other molecular tools to interfere with these two proteins." (PMID 34360603, 2021). "Given the prognostic role and the selective expression of CR-1 and Nodal on cancer cells, they represent archetypes for targeted therapy." (PMID 34360603, 2021). "More importantly, the atypical expression of CR-1 has been shown to be connected with clinically aggressive behaviour and patients’ survival in these cancers." (PMID 31455359, 2019).
cancer (continued). "In agreement with our findings, several previous IHC studies of CR-1 have also revealed the relationship between CR-1 expression and clinicopathologic features on other cancers." (PMID 31455359, 2019). "Shedding of CR-1 by GPI-phospholipase D can release a soluble form of CR-1 in human milk, serum or in various types of cancer cells and is also in the conditioned medium from several cell lines and from cells that are ectopically overexpressing this protein." (PMID 30373174, 2018). "The EGF-CFC family molecule TDGF1 (Cripto, CR-1) plays important roles in the tumorigenesis and aggressiveness of many cancers." (PMID 28620148, 2017). "A growing body of evidence has been emerging that CR-1 is overexpressed in several types of cancer, including human embryonal carcinoma, and colon, brain, liver, breast, lung cancers." (PMID 28431580, 2017). "Consistent with our findings, anti-EGF-like domain CR-1 antibodies produce apoptosis in cancer cells through significant reduction in activation of the AKT, c-Jun-NH2-terminal kinase, and p38 kinase signaling pathways." (PMID 26472984, 2015). "CR-1 is upregulated in several malignant tumors, including gastric cancer, breast cancer, and ovarian cancer, while being downregulated in normal tissue." (PMID 26472984, 2015). "It has been suggested that CR-1 functions in conjunction with Nodal in cancer stem cell populations to promote tumorigenesis in melanoma and testicular tumors." (PMID 25596738, 2015). "Evidence suggests that CR-1 is also involved in the pathogenesis and progression of human carcinoma." (PMID 21863025, 2011). "CRIPTO-1 (CR-1) is involved in the pathogenesis and progression of human carcinoma of different histological origin." (PMID 21863025, 2011). "CR‐1 is an essential process in cancer growth, maintenance, and metastasis." (PMID 35949510, 2022). "Further investigation targeting CR-1 will lead to the development of agents to treat cancer." (PMID 33567764, 2021). "Moreover, cancer cells that show high levels of CR-1 and/or Nodal display more aggressive phenotypes in vitro, while in vivo their expression correlates with a worse prognosis in several human cancers." (PMID 34360603, 2021). "However, in recent years, the function of CR-1 in cancer cells has been described and suggested to be a good target of cancer treatment." (PMID 33567764, 2021). "Several studies demonstrated the potential role of CR-1 in the progression of cancer, so it was speculated that this protein was involved in the regulation and/or activation of signal cascades that promote cell survival and proliferation." (PMID 34360603, 2021). "In addition, CR-1 and Nodal overexpression is correlated with a worse prognosis in several human cancers." (PMID 34360603, 2021). "A novel and interesting approach to interfere and target CR-1 expressing cancer cells could be the usage of bispecific antibodies (BiAbs) in association with a T cell-based therapy." (PMID 34360603, 2021). "Expression of CR-1 is observed in early embryogenesis and often in the development of many cancers." (PMID 33567764, 2021). "Cripto‐1 (CR‐1) is related to the biological behaviour and prognosis of carcinomas." (PMID 32697011, 2020). "Cripto-1 (CR-1) has been reported to be involved in the development of several human cancers." (PMID 31455359, 2019). "Cripto-1 (CR-1) is involved in various processes in embryonic development and cancer." (PMID 25658584, 2015). "Though small in size, such CR-1 high subpopulation may eventually play crucial role in progression of cancer." (PMID 25658584, 2015). "Positive feedback driven heterogeneity in expression of CR-1 may play crucial role in phenotypic diversification of cancer cells." (PMID 25658584, 2015). "Clearly, further research regarding the selective expression of CR-1 in certain malignancies may be valuable for unraveling its multifaceted role in development and in cancer." (PMID 25596738, 2015).
cancer (continued). "Involvement of CR-1 in embryonic pattern formation and progression of cancers is well documented." (PMID 25658584, 2015). "The high frequency of expression of CR-1 in different carcinoma types and the low expression in normal tissues suggest that this protein might be a suitable target for cancer therapy." (PMID 21863025, 2011). "Previous findings in different carcinoma types suggested that cell lines with levels of CR-1 mRNA >0.7 as compared with SK-Br-3 cells might express a biologically active CR-1 protein." (PMID 21863025, 2011). "Moreover, many data indicate CR-1 as a promising target for cancer therapy." (PMID 31455359, 2019). "Therefore, CR-1 expression level could be used to predict cancer progression, metastasis and prognosis of ccRCC patients." (PMID 31455359, 2019). "Presently, we speculate that CR-1 might initiate EMT early in the course of cancer progression." (PMID 25596738, 2015). "Indeed, it has been observed that treatment with antisense oligonucleotides directed against CR-1 results in a significant inhibition of the in vitro and in vivo growth of human carcinoma cells of different histological origin, in which CR-1 can function as autocrine or paracrine growth factor." (PMID 21863025, 2011). "Our capture/quantitative ELISA was able to detect CR1/CR3 at picograms/mL and demonstrated their expression in the sera from normal/cancer patient donors, establishing their soluble protein characteristics." (PMID 39518018, 2024). "We employed CR1 to block exogenous activation of C3 and detected a weakened expression of p-STAT3 and IL-6 compared with AG490-treated cancer cells." (PMID 31928530, 2020). "Cripto‐1 (CR‐1) is a member of the epidermal growth factor‐cripto FRL1 cryptic family, which is overexpressed in various carcinomas." (PMID 32697011, 2020). "We found some downregulated proteins in MM-PC that seem to play important role in cancer immune evasion mechanisms such as: HLA-A, HLA- DRB5, CR1, and CR2." (PMID 26807199, 2015). "Two rat IgM MoAbs have been reported that bind to the EGF-like domain of CR1 and can detect this oncofetal protein in the cancer tissue of the colon/lung/breast but not in their respective normal counterparts." (PMID 39518018, 2024). "In particular, the EGF-like domain of CR-1 has been shown to induce mitogenic signaling, and the mere addition of refolded peptides resembling the EGF-like domain of CR-1 has been shown to stimulate growth of several types of cancer cell lines." (PMID 26472984, 2015). "The results of the cancer-related pathway analysis showed that the high expression of these antigen genes was mainly related to the activation of the epithelial–mesenchymal transition (EMT) pathway, whereby CR1 and SEMA7A were involved in up to 41% of cancer types." (PMID 35955933, 2022). "However, due to the lack of elucidation of the function of CR-1, studies focusing on CR-1 as a target of cancer therapy was limited for a long time." (PMID 33567764, 2021). "Like all normal cells, cancer cells are protected from autologous complement attack by several specific cell-surface complement inhibitors: CD55 (decay accelerating factor, DAF), CD46 (membrane cofactor protein, MCP), CD59, and CD35 (complement receptor type 1, CR1)." (PMID 31024572, 2019). "In addition, because PSA biochemical recurrence does not always appear to be an accurate predictor of cancer specific death in men with PCa, the impact of CR-1 expression on overall survival has yet to be addressed." (PMID 25596738, 2015).
bacterial infections (9 papers, 2012 to 2025). "Among these genes, certain genes involved in the complement cascade were expressed at lower levels in the resistant family (c2, c6, cr1 or cd59), in contrast to what was found in head kidney samples after bacterial infection." (PMID 39712009, 2024). "Compared with neutrophil CD64, neutrophil complement receptor 1 (CR1/CD35) seems to be a more specific bacterial infection marker." (PMID 34844193, 2021). "Expression of CR1 on neutrophils is increased upon stimulation, especially during a bacterial infection." (PMID 28273167, 2017). "In neutrophils, CR1, CR3, FcγRI, and FcγRII were upregulated, while FcγRIII was downregulated in bacterial infections." (PMID 22536142, 2012).
neurodegenerative disease (5 papers, 2014 to 2025). A disorder of the central nervous system characterized by gradual and progressive loss of neural tissue and neurologic function. "Polymorphisms that alter CR1 gene expression or protein activity are also common worldwide and have been associated with different infectious, autoimmune, and neurological/neurodegenerative diseases." (PMID 31824479, 2019).
cardiovascular disease (2 papers, 2018 to 2020). "Validation of the susceptibility gene CR1 unveiled that cigarette smoke might prevent COPD-related cardiovascular disease." (PMID 33457407, 2020).
infectious disease (2 papers, 2017 to 2023). A disorder directly resulting from the presence and activity of a microbial, viral, or parasitic agent in humans. "CR1 genetic variants in exon 29 have been associated with expression levels, C1q or C3b binding and increased susceptibility to several infectious diseases." (PMID 28520715, 2017). "CR1 genetic variants in exon 29 are associated with CR1 expression levels, C1q or C3b binding activity and increased susceptibility to various infectious diseases." (PMID 28520715, 2017). "The samples utilized in this study are from different case-control cohorts investigated for possible associations of CR1 variants with different infectious diseases (unpublished data)." (PMID 28520715, 2017).
heart disease (1 paper, 2024). "Mutations in the RAF1 CR1 functional domain, reported in multiple large-scale heart disease cohorts, may be associated with the disease." (PMID 38952713, 2024).
neurological disease (1 paper, 2025). "Also, 59 unique proteins were associated with AD, and 10 of them (17%) showed an association with AD and an additional neurological disease (CTF1, NSF and PRSS53 with PD; SIGLEC9 with ALS; CR1, CTSH, PARP1 and PVR with MS; LRRC37A2 with both PD and ALS; and IDUA with PD, ALS and MS)." (PMID 40037332, 2025).
renal disease (1 paper, 2021). "Our major ideas–including the analogy of HAE to C1-INH insufficiency in the CNS, CR1 and apoE as factors in AD, plus Factor H in ocular and renal disease – are grounded in human studies." (PMID 33746710, 2021).
CR1 also shares sentences with these, for which no sentence is quoted: follicular dendritic cell sarcoma (8 papers); asthma (4); MALT lymphoma (4); haemoglobinopathies (3); inflammatory myofibroblastic tumor (3); lupus nephritis (3); spindle cell neoplasm (3); acute myeloblastic leukemia (2); Chagas disease (2); Cirrhosis (2); dendritic cell neoplasms (2); dendritic cell sarcoma (2); esophageal squamous cell carcinoma (2); follicular lymphoma (2); histiocytoma (2); Hodgkin disease (2); meningeal (2); meningioma (2); Parkinson disease (2); staphylococcus aureus infection (2); undifferentiated carcinoma (2); vascular dementia (2); acquired immune deficiency syndrome (1); acute leukemia (1); acute monoblastic leukemia (1); adenocarcinoma (1); agammaglobulinemia (1); age-related macular degeneration (1); amyotrophic lateral sclerosis (1); Arthritis (1).
A further 85 diseases each share a sentence with CR1 in 1 paper.